CRH (corticotropin releasing hormone)
Diseases named in the same sentence as CRH in open-access papers (continued):
Sharing a sentence is not in itself a finding about the gene and the disease.
metastatic cancer (1 paper, 2015). A carcinoma which has spread from the original site of growth to another anatomic site. "It is of interest that MCs can secrete large quantities of VEGF especially in response to CRH, which can be secreted by MCs and by metastatic cancer cells." (PMID 26377554, 2015).
metastatic tumor (1 paper, 2013). "Thus indicating, as previously suggested, that IL-6 may act in metastatic tumor-bearing hosts as a CRH-independent pituitary stimulator." (PMID 23517603, 2013).
morphine dependence (1 paper, 2012). Strong dependence, both physiological and emotional, upon morphine. "Given that the increase of Fos/ΔFosB within CRH neurons during morphine dependence was attenuated in ADX animals, it might be suggested a role for Fos/ΔFosB in the regulation of CRH expression by GC in the extended amygdala." (PMID 23185589, 2012).
multiform glioblastoma (1 paper, 2016). "Two other metabolic pathways - the signaling of the corticotropin releasing hormone and the multiform glioblastoma – include large subsets of dysregulated genes." (PMID 26932723, 2016).
myocardial infarction (1 paper, 2017). Gross necrosis of the myocardium, as a result of interruption of the blood supply to the area, as in coronary thrombosis. "For example, copeptin levels spike in concert with cortisol and corticotropin-releasing hormone within hours of acute myocardial infarction onset." (PMID 28638629, 2017).
neuropathy (1 paper, 2015). A disorder affecting the nervous system that manifests with pain, tingling, numbness, and/or muscle weakness. "However, little has been found yet as to which cells express endogenous CRH in neuropathy." (PMID 25880204, 2015). "The role of CRH and its receptors (CRH-R1 and CRH-R2) in neuropathy has not yet been well-defined." (PMID 25880204, 2015).
ovarian failure (1 paper, 2023). "In females under prolonged stress, the exaggerated CRH (corticotropin-releasing hormone) effects could further cause inhibition of ovarian steroidogenesis, ovarian failure, and follicular atresia." (PMID 37215366, 2023).
parkinsonian disorder (1 paper, 2024). A group of disorders which feature impaired motor control characterized by bradykinesia, MUSCLE RIGIDITY; TREMOR; and postural instability. "The absence of longitudinal clinical data prevented us from assessing if pre-symptomatic SAA+ would progress to a symptomatic parkinsonian disorder, as well as how CRH levels change over the course of the disease." (PMID 39605973, 2024). "Furthermore, we show the potential of CRH as a novel biomarker for atypical parkinsonian disorders, namely MSA and PSP." (PMID 39605973, 2024). "We highlight CRH as a possible biomarker for parkinsonian disorders." (PMID 39605973, 2024). "The authors highlight CRH as a potential biomarker for parkinsonian disorders." (PMID 39605973, 2024).
pituitary disease (1 paper, 2022). "Previously, we have demonstrated that in patients with a history of pituitary disease after CRH administration, the HPA axis may be effectively stimulated even if copeptin secretion is attenuated." (PMID 36359377, 2022).
pneumococcal infection (1 paper, 2017). Infections with bacteria of the species streptococcus pneumoniae. "Initial studies investigated the time‐associated effect of CRH administration during pneumococcal infection." (PMID 28057851, 2017). "In conclusion, our studies reveal the potential novel use of nasal delivery of CRH in control of overt inflammatory responses localized along respiratory tissues with the potential in reducing mortality risks associated with pneumococcal infection." (PMID 28057851, 2017). "This study will determine the role of CRH and dexamethasone in mediating mortality, and how they influence inflammatory responses during pneumococcal infection." (PMID 28057851, 2017). "Interestingly, intranasal administration of antalarmin significantly reduced the protective effect of CRH, suggesting that endogenous ligation of CRH to its cognate receptor CRHR1 could be mediating responses during pneumococcal infection." (PMID 28057851, 2017).
pregnancy disorder (1 paper, 2015). A disorder that is related to pregnancy. "Placental CRH expression is predictive of gestational length and is influenced by pregnancy disorders." (PMID 26457081, 2015).
pregnancy-induced hypertension (1 paper, 2013). "High level of corticotropin-releasing hormone (CRH) is a known risk factor for premature rupture of membranes, preterm labor, eclampsia and pregnancy-induced hypertension." (PMID 23706121, 2013).
pulmonary hypertension (1 paper, 2023). Increased pressure within the pulmonary circulation due to lung or heart disorder. "Nonetheless, we demonstrated for the first time that attenuated CRH synthesis by overexpression of ACE2 is sufficient to promote protection against chronic hypoxia-induced pulmonary hypertension." (PMID 37638323, 2023). "Further investigation of the mechanisms whereby CRH activation may contribute to the pathophysiology of pulmonary hypertension is still needed." (PMID 37638323, 2023).
Respiratory insufficiency (1 paper, 2022). "The offspring of corticotropin-releasing hormone-deficient (CRH-KO) mice, who are themselves deficient in glucocorticoids, exhibit abnormal pulmonary development and consequently, respiratory insufficiency." (PMID 35589861, 2022).
Seizure (1 paper, 2018). A seizure is an intermittent abnormality of nervous system physiology characterized by a transient occurrence of signs and/or symptoms due to abnormal excessive or synchronous neuronal activity in the brain. "Genetically-targeted ablation of hippocampal CRH neurons in vivo impaired object recognition memory and substantially enhanced the severity of kainic acid-induced seizures." (PMID 29346425, 2018).
Shock (1 paper, 2011). The state in which profound and widespread reduction of effective tissue perfusion leads first to reversible, and then if prolonged, to irreversible cellular injury. "It was not possible to determine whether the absence of increase in CRH depends on septic shock duration, intensity or both since all patients died from severe septic shock." (PMID 22073145, 2011).
social phobia (1 paper, 2024). An anxiety disorder characterized by an intense, irrational fear of one or more social or performance situations in which the individual believes that he or she will be scrutinized by others. "Additionally, single nucleotide polymorphisms (SNPs) in the CRH gene are linked to behavioral inhibition, a childhood risk factor for PD and social phobia." (PMID 39025836, 2024).
temporal lobe epilepsy (1 paper, 2018). A localization-related (focal) form of epilepsy characterized by recurrent seizures that arise from foci within the temporal lobe, most commonly from its mesial aspect. "Thus we hypothesized that manipulating hippocampal CRH neurons would be sufficient to modulate seizure susceptibility in the systemic KA model of temporal lobe epilepsy." (PMID 29346425, 2018). "In the present study, we expand on our initial characterization by probing CRH interneurons’ relevance to hippocampus-dependent processes such as emotional behavior and recognition memory, as well as their impact on seizures in a model of temporal lobe epilepsy." (PMID 29346425, 2018).
vulvar carcinoma (1 paper, 2024). "Our present study should be considered as a preliminary effort to outline the role of CRH and UCN pathways in vulvar cancer pathophysiology." (PMID 37382757, 2024).
tumor (65 papers, 2007 to 2026). "Quantification showed the highest CRH expression in the semimalignant superficial and nodular BCCs, and not in SCCs, thus failing to confirm the association with a more aggressive tumor phenotype." (PMID 40917468, 2025). "The extremely rare occurrence of corticotropin-releasing hormone (CRH)-producing tumours (<1%) should only be factored in after more common causes have been excluded." (PMID 39816312, 2024). "Less frequently, an extra-pituitary ACTH- or corticotropin-releasing hormone (CRH)-producing tumor can be the cause." (PMID 36644045, 2022). "A significant difference between normal and tumor skin cells has been observed regarding the expression of hormones associated with the CRH-POMC axis." (PMID 34068618, 2021). "The involvement of the hormones associated with corticotropin-releasing hormone (CRH)-proopiomelanocortin (POMC) axis in the tumor development process has also prompted the interest of researchers." (PMID 29854027, 2018). "We can thus provide data on constitutive and modulated gene expression in adenomatous corticotropes, associated with tumor features and response to CRH and steroids." (PMID 27220856, 2017). "To investigate if tumor-derived IL-6 is directly linked to changes in CRH expression under in vivo conditions, we inoculated intravenously control B16-F10 cells and B16-F10 cells transfected with siRNA specific for IL-6 (B16-F10/IL-6-siRNA)." (PMID 23517603, 2013). "Tumour advancement, as assessed by increasing tumour stage, was associated with significantly increased immunohistochemical positivity for CRH and FasL (P<0.05 between stage II and stage IV tumours)." (PMID 17667919, 2007). "Expression of CRH and FasL were positively associated with higher tumour stage." (PMID 17667919, 2007). "Positivity for CRH or FasL expression was associated with higher tumour stage." (PMID 17667919, 2007). "Furthermore, this study associates the expression of CRH with tumour advancement to higher stages, thus proposing that the tumour might benefit from CRH secretion." (PMID 17667919, 2007). "In addition, we present data that might offer an explanation on the association of intratumoral CRH with tumour advance." (PMID 17667919, 2007). "The diagnosis was based on immunostaining for CRH, plasma CRH measurement, in vitro tumor studies, or gradient of CRH concentration." (PMID 41334448, 2025). "Tumor burden has been shown to elicit anxiety-like behaviors in mice, accompanied by the activation of CRH neurons in the central medial amygdala (CeMCRH)." (PMID 41163091, 2025). "The importance of this CRH augmentation at the transition from precancer to cancer has been also considered as an inducer of angiogenesis and tumor cell migration." (PMID 37382757, 2024). "As a result, tumor growth in CRH-Cre/hM3Dq mice was greater than that in WT/hM3Dq mice (two-way ANOVA followed by the post-hoc Bonferroni test, *p < 0.05, ***p < 0.001 vs. WT/hM3Dq)." (PMID 36732798, 2023). "The leftover tumor cells are stimulated to expand until they form a corticotroph adenoma and produce more proopiomelanocortin when CRH is elevated." (PMID 37332454, 2023). "ECS is caused by the excessive synthesis and secretion of adrenocorticotropic hormone (ACTH) and/or corticotropin releasing hormone (CRH) from tumor cells, usually of neuroendocrine origin." (PMID 34033277, 2021). "It is worth noting that many genes were dramatically upregulated specifically in ACTH+&CRH + pheochromocyte when compared with the other tumor cell types, such as GAL, POMC, PNMT, and CARTPT." (PMID 34905486, 2021). "By contrast, regarding CRH/CRHR1 signaling, a pro-inflammatory and, therefore, tumor-promoting effect, was observed in colitis-associated cancer." (PMID 32429087, 2020). "Another pathway active during the Vascular Endothelial Growth Factor (VEGF)-induced tumor angiogenesis is the CRH/CRHR1 signaling, as one of the mechanisms in colitis-associated CRC." (PMID 32429087, 2020).
tumor (continued). "Prolonged administration of CRH, or a CRH‐secreting tumor, leads to increases in corticotroph cell mass as well as ACTH output." (PMID 32672906, 2020). "The gold standard in the diagnosis of EAS is BIPSS and confirmation of EAS requires positive staining for ACTH or CRH in tumor cells." (PMID 33237923, 2020). "In parallel, we investigated any possible implications of CRH-driven signaling in the regulation of tumor responsiveness to endogenous anti-tumor immuno-mediated cytotoxic responses." (PMID 31614860, 2019). "Nonetheless, all of our functional analysis are still preliminary and require future functional validation using improved tumor models taking into account the complexity of the CRH signaling network." (PMID 27695045, 2016). "Concurrent alterations in apoptotic behavior and AKT pathway signaling of tumor cells have also been observed following treatment by CRH and UCN2." (PMID 27695045, 2016). "Immunohistochemical studies using antibodies against pituitary tropic hormones showed that the number of ACTH and CRH-secreting cells in pituitary and extrapituitary tumours is much greater than the number of cells expressing other hormones." (PMID 23509456, 2013). "CRH expression in the hypothalamic PVN was significantly lower in metastatic B16-F10-bearing mice than in non-tumor-bearing controls, whereas serum IL-6 increased." (PMID 23517603, 2013). "Corticotropin-releasing hormone and its receptors have been detected in a number of primary human tumours." (PMID 17667919, 2007). "Thereafter, CRH and its receptors have been localised in a number of tumours, but the role of the neuropeptide in the biology of cancer is still unclear." (PMID 17667919, 2007). "In this case, tumour advancement was positively correlated with the comparatively estimated amount of CRH or FasL produced by tumour cells (P<0.05 between stage II and stage IV tumours)." (PMID 17667919, 2007). "Although no alteration was observed in the expression of CRHRs among the three stage-groups of tumours, more stage IV than stage II tumours simultaneously expressed the CRH, CRHR1 and FasL peptides." (PMID 17667919, 2007). "We propose that tumour CRH acts in a paracrine–autocrine way to favour survival and progression of the tumour by promoting its immune privilege, whereas it has no direct effect on tumour cells growth rate." (PMID 17667919, 2007). "Of note, CRH-stimulated angiogenesis and promoted tumour growth in vivo in a model of mice inoculated with human epithelial tumour cells." (PMID 17667919, 2007). "Based on these data, the level of CRH expression appears to increase with the degree of malignancy, suggesting a tumor promoting ability that may be partially mediated by its immunosuppressive function." (PMID 40917468, 2025). "These complex interactions, potentially mediated by truncated elements of the skin-specific HPA axis, may contribute to the heterogeneity of CRH effects in the tumor microenvironment." (PMID 40917468, 2025). "Therefore, it is believable that the central role of CRH in tumor is likewise mainly via the indirect way through HPA axis-mediated stress." (PMID 38616821, 2024). "Additionally, vasopressin V3 receptor genes are overexpressed in pituitary tumors that secrete ACTH, and both arginine vasopressin and CRH stimulate the growth of a corticotropic tumor cell line." (PMID 37332454, 2023). "In addition, fiber photometric recordings in 4T1 tumors also indicated that direct optogenetic stimulation of LPGi-projecting CRH neurons in the CeM (CeMCRH→LPGi circuit) also induced a robust increase in fluorescent signals of GRABNE2h in tumor tissue." (PMID 37847562, 2023). "When HeLa cells were exposed to CRH, a significant increase in both FasL transcription and FasL translation was detected, reinforcing the hypothesis that CRH is involved in tumor immunoescape." (PMID 36552294, 2022). "The IHC of the dissected tumor confirmed the diagnosis with positive staining for CRH and ACTH." (PMID 34905486, 2021).
tumor (continued). "Furthermore, we believed that the rare Case 1 harbor the ACTH-dependent CS is due to the presence of the identified novel tumor cell type of ACTH+&CRH + pheochromocyte, which secretes both ACTH and CRH." (PMID 34905486, 2021). "Thus, the majority of our analysis focused on the validation of novel tumor cell type and their multiple hormones-secreting functions, namely, CRH secretion function, ACTH secretion function, and catecholamine secretion function." (PMID 34905486, 2021). "An operation was also chosen in order to examine whether the tumor was an ACTH/CRH-secreting lesion or if there were any microadenomas that could be observed during the operation." (PMID 32423480, 2020). "An operation was chosen in order to examine whether the tumor was an adrenocorticotrophic hormone/corticotropin-releasing hormone-secreting lesion or if there were any microadenomas that could be observed during the operation." (PMID 32423480, 2020). "In prostatic cells it has been found that CRH and Ucn2 affect apoptosis of tumor cells." (PMID 27695045, 2016). "Conclusively, our analysis clearly demonstrated epigenetic silencing of CRHBP hence showing for the first time that a member of the CRH-system is epigenetically silenced in tumor cells and thus providing strong evidence for an involvement of CRH members in human tumorigenesis." (PMID 27695045, 2016). "Moreover, functional studies demonstrated in vitro that migration of tumor cells can be enhanced by CRH protein." (PMID 27695045, 2016). "Furthermore, tumour advancement was positively correlated with the percentage of tumours simultaneously expressing CRH, CRHR1 and FasL." (PMID 17667919, 2007). "However, our lack of knowledge on the role of CRH in cancer biology, limits our leeway for testing CRH antagonists against specific and vital molecular functions of the tumour." (PMID 17667919, 2007). "However, a positive staining was observed for CRH, confirming ectopic CRH production by the tumor." (PMID 40927294, 2025). "The regulation of the local immunological profile (e.g., CRH/CRHRs), dysfunctions of enteroprotective role of NPs on epithelial cells (e.g., NT/NT-R), as well as structural-functional changes in enteric nervous system innervation of the tumor are also important." (PMID 32429087, 2020). "However, patients with a large tumor and an extremely high cortisol level may lack a response in the CRH test." (PMID 31726770, 2019). "The potential relevance of CRH-system alterations in tumor biology has been suggested by a number of reports showing that urocortins as CRH ligands may inhibit tumor growth via effects on vascularization, promote the apoptosis of endothelial cells, and downregulate VEGF expression in vivo." (PMID 27695045, 2016). "Thus, the effect of CRH on tumour growth appears to be tissue-specific and the final result in vivo might differ from the observed effects in vitro due to the contribution of several factors." (PMID 17667919, 2007). "The KC1 subtype exhibited prominent activation of the SPP1 and CRH pathways, aligning with established roles of the CXCL9‐SPP1 macrophage polarity axis in promoting tumour progression and immunotherapy resistance." (PMID 41025426, 2025). "The results indicate that, through CRHR1 activation, CRH promotes cell growth through NF-κB/IL-6/JAK2/STAT3 signaling and tumor angiogenesis through NF-κB/VEGF signaling." (PMID 36552294, 2022). "To validate this finding, we performed additional IHC staining experiments on paraffin-embedded serial slices with similar tissue regions from the tumor specimen esPHEO_T3 using antibodies against CgA, ACTH, POMC, CRH, TH, and GAL." (PMID 34905486, 2021). "Corticotropin-releasing hormone (CRH) hyperactivity induced by rapid cortisol reduction is thought to be one of the pathogenesis of its marked ACTH elevation and aggressive tumor enlargement." (PMID 34220707, 2021).